DLD (dihydrolipoamide dehydrogenase)
Diseases named in the same sentence as DLD in open-access papers (continued):
Sharing a sentence is not in itself a finding about the gene and the disease.
tumor (continued). "After knockdown of DLD expression, it was found that DLD regulated metabolic pathways by suppressing the intracellular NAD+/NADH ratio, which then in turn suppressed tumor cell proliferation detected by MTT assay." (PMID 37123026, 2023). "We found that FDX1, DLD, PDHA1, MTF1, GLS, and CDKN2A showed differential expression levels between normal and tumor tissues." (PMID 37711156, 2023). "We found that DLD, DLAT, PDHA1, and CDKN2A were differentially expressed between normal and tumor tissues; CDKN2A was upregulated and the other genes were downregulated in the tumor tissues." (PMID 37711156, 2023). "Nine CRGs were differentially expressed between tumor and normal tissues, among which NFE2L2, SLC31A1, FDX1, DLD, DLAT, and DLST were lowly expressed in tumor tissues, and ATP7B, CDKN2A, and GCSH were highly expressed in tumor tissues (p<0.05)." (PMID 37205181, 2023). "Of note, seven out of ten pivotal CRGs, which were identified in Science article, showed significantly altered expression patterns, with CDKN2A exhibited higher and DLAT, DLD, FDX1, LIAS, MTF1, PDHB exhibited lower expression in tumor tissues (P<0.05)." (PMID 37384293, 2023). "In epithelial cells, FDX1 and DLD were highly expressed in all kinds of cells, and CDKN2A was mainly expressed in tumor." (PMID 37239416, 2023). "Among them, the expression levels of CDKN2A, GLS and LIPT1 were significantly upregulated whereas the expression levels of DLAT, DLD, FDX1, MTF1 was significantly downregulated in tumor samples." (PMID 37072493, 2023). "In tumor cell-enriched region, the expression of COPS5, DLAT, DLD, FDX1, NFE2L2, PDHA1 and PDHB in the high score group is higher than that in the low score group, while the opposite is true for DLST, GCSH and LIPT2 (P <0.05)." (PMID 36618352, 2022). "Among them, 7 genes (DLAT, DLD, GCSH, LIAS, LIPT1, PDHA1, and PDHB) were upmodulated, whereas 3 genes (ATP7B, FDX1, and SLC31A1) were downmodulated in the tumor group in contrast with the normal group (p < 0.05)." (PMID 36046242, 2022). "We found that LIAS and CDKN2A were significantly upregulated in tumor samples, and FDX1, DLD, DLAT, PDHA1, PDHB, MTF1, and GLS were significantly downregulated in tumor samples." (PMID 36531222, 2022). "Based on the analysis of scRNA-seq, the expression of FDX1, DLD and SLC31A1 was much higher in non-tumor tissues than those in tumor tissues, consistent with our findings from a bulk sequencing analysis." (PMID 36733399, 2022). "Cell experiments in this study suggest that the DLD gene is abnormally, highly expressed in RCC, and participates in regulating the migration ability of tumor cells." (PMID 36591111, 2022). "A heatmap showed that the levels of expression of ATP7B, DLAT, DLD, LIAS, and SLC31A1 were upregulated and the levels of expression of DBT, FDX1, and PDHB downregulated in tumor samples." (PMID 36092880, 2022). "Subsequently, we detected the expression of these CRGs in tumor and normal samples and found that 6 genes, FDX1, LIAS, DLD, DLAT, PDHB and MTF1, were significantly downregulated in tumors, while 2 genes, GLS and CDKN2A, were significantly upregulated." (PMID 36246586, 2022). "The expression of MTF1, NLRP3, and SLC31A1 was positively related with ImmuneScore, StromalScore, and ESTIMATEScore in almost all types of tumor, whereas ATP7B, DLAT, DLD, LIAS, PDHA1, and PDHB were significantly negatively correlated with the scores." (PMID 36387247, 2022). "CDKN2A, GLS, LIPT1, and PDHA1 were up-regulated in tumor samples, and FDX1, DLD, MTF1 were down-regulated in tumor samples." (PMID 36176287, 2022). "Some genes were more different in tumor samples (FDX1; Dihydrolipoamide Dehydrogenase, DLD)." (PMID 37239416, 2023).
tumor (continued). "Moreover, further analysis was made to investigate the mRNA expression level of CRGs between normal and CRC samples, and we found that the expressions of FDX1, DLD, DLAT, PDHB, and MTF1 were significantly decreased, whereas LIPT1, GLS, and CDKN2A were significantly upregulated in tumor samples." (PMID 37006250, 2023). "Although the involvement of DLD in the constitutive pyruvate dehydrogenase complex (PDC) and α-ketoglutarate dehydrogenase complex (KGDC) has been identified as an important metabolic target in cancer, the role of DLD in the metabolism of tumor cells is less explored." (PMID 37113760, 2023). "We found that five cuprotosis molecules, DLAT, PDHA1, FDX1, GLS and CDKN2A, were significantly different between paired tumour and adjacent non-tumour samples from the TCGA-STAD cohort, and LIAS, DLD, DLAT and MTF1 were significantly different among the four pathologic T categories 1–4." (PMID 36895378, 2023).
cancer (28 papers, 2012 to 2025). A tumor composed of atypical neoplastic, often pleomorphic cells that invade other tissues. "In addition, the present findings suggested for the first time, to the best of our knowledge, that DLD expression was associated with the level of infiltration by cancer-associated fibroblasts in HNSC, KIRC, LUSC, KIRP, and THCA." (PMID 37123026, 2023). "In total, 14 DECRs were identified, of which six regulators (MTF1, DLST, NLRP3, DBT, FDX1, and DLD) were downregulated in cancer tissues." (PMID 36672336, 2023). "Our study found that the expression of DLD was mainly positively correlated with some functional states of cancer cells." (PMID 37113760, 2023). "The DLD gene is a key gene that promotes copper death; however, the specific role of DLD in the prognosis and immune regulation of various cancers remains unexplored." (PMID 38077227, 2023). "A total of 6 CRSGs were screened out, including CDKN2A, GLS, FDX1, PDHA1, PDHB, and DLD; most of them have been reported in the direct regulation of cuproptosis and cancer progression." (PMID 37287976, 2023). "For the results based on the data from the TCGA and GTEx evaluated with GEPIA2.0, we found that the expression level of DLD was upregulated in 4 cancer types including DLBC, GBM, PAAD, and THYM." (PMID 37113760, 2023). "Moreover, the expression of DLD was negatively correlated with myeloid dendritic cell infiltration in TGCT and cancer-associated fibroblast infiltration in KIRC, KIRP, and THCA." (PMID 37113760, 2023). "The mRNA and protein expression of DLD differs in most cancers." (PMID 38077227, 2023). "The exact function of the cuproptosis-related gene dihydrolipoamide dehydrogenase (DLD) and its role in pan-cancer is unknown." (PMID 38077227, 2023). "DLD, a positive regulator of cuproptosis, enhances copper-dependent cell death, which may provide new ideas for the therapeutic action of certain cancer-targeted drugs." (PMID 37113760, 2023). "Furthermore, we conducted the correlation analysis in pan-cancer, and the result demonstrated that DLD and PDHA1 were the two genes having the most significantly positive association (Correlation coefficient = 0.39)." (PMID 36518756, 2022). "However, there was a negative correlation between DLD expression and cancer-associated fibroblast infiltration in KIRC, LUSC, KIRP and THCA." (PMID 37123026, 2023). "In this pan-cancer analysis, we systematically profiled the expression and prognostic value of eight well-characterized cuproptosis-related genes—FDX1, LIAS, LIPT1, DLD, DLAT, PDHA1, PDHB, and SLC31A1—across 34 cancer types." (PMID 40601654, 2025). "In Cuproptosis-related genes, SPC25 was positively correlated with GCSH, CDKN2A, PDHB, PDHA1, DLAT, DLD, and SLC31A1 of pan-cancer." (PMID 38605119, 2024). "Among these cancers, the cuproptosis key genes, LIAS, FDX1, and DLAT tended to show copy number deletion, while DLD tended to show copy number amplification." (PMID 38573998, 2024). "Combined with 19 genes related to cuproptosis in the current cancer database, NFE2L2, PDHA1, PDHB, DLD, and GLS showed significant differences between the two groups." (PMID 38200445, 2024). "Our study showed that MRPL13 and its associated genes were significantly correlated with cuproptosis-related genes across cancers, with the most significant ones being FDX1, GCSH, DLST, and DLD." (PMID 37827692, 2023). "The results showed that cuproptosis-related genes such as PDHB, PDHA1, DLAT, DLD, LIPT1 were significantly positively correlated with FDX1 in pan-cancer." (PMID 35991547, 2022). "The transcriptional levels of DLAT, FDX1, DBT, DLD, PDHB, and GCSH negatively correlate with methylation in part of tumors (> 7 cancer types)." (PMID 36209249, 2022). "The correlation calculated for all paired samples (33 cancer types) revealed that of the 10 cuprotosis molecules, six (DLAT, DLD, MTF1, CDKN2A, GLS and FDX1) may be negatively regulated by many miRNAs." (PMID 36895378, 2023).
infection (6 papers, 2013 to 2023). The state of being infected such as from the introduction of a foreign agent such as serum, vaccine, antigenic substance or organism. "Three infection-associated proteins in S. suis—muramidase-released protein (MRP), glyceraldehyde-3-phosphate dehydrogenase (GAPDH), and DLD, a novel putative dihydrolipoamide dehydrogenase—have been previously identified by immunoproteomic assays." (PMID 33671673, 2021). "For example, DLD, a subunit of multiple metabolic enzyme complexes, has up to a fivefold increase in acetylation at multiple sites during infection." (PMID 30470744, 2018). "However, increased levels of the enzymes such as MDH and DLD, that could be responsible for ROS generation in the resistant Charlton, were mainly manifested at an early stage of the infection process." (PMID 23776450, 2013). "Mitochondrial proteins are among these dually modified proteins, in agreement with our finding of infection-enhanced acetylations on TCA cycle proteins, including PDHB, DLAT, and DLD, at sites known as ubiquitinated." (PMID 30470744, 2018). "The three protein spots identified as repressed during infection matched a component of the eukaryotic elongation factor 1B (EEF 1B) complex (spot ID 54), a dihydrolipoamide dehydrogenase (spot ID 112) and a GH17 endo‐1, 3‐β‐glucanase (spot ID 74)." (PMID 25764246, 2016).
mitochondrial disease (4 papers, 2019 to 2024). "Dihydrolipoamide dehydrogenase (DLD) deficiency is a recessive mitochondrial disease caused by variants in DLD, the E3 subunit of mitochondrial α-keto (or 2-oxo) acid dehydrogenase complexes." (PMID 39163131, 2024). "Autosomal recessive pathogenic variants in human DLD, which encodes DLD that functions as the common E3 subunit of 4 mitochondrial matrix enzymes, lead to a debilitating primary mitochondrial disease." (PMID 36278487, 2022). "Many mitochondrial disease-related altered proteins also formed part of the energy network (DLD, NDUFA4, NDUFB5, NDUFB6, NDUFB9, NDUFS1, NDUFA12 and UQCRB) and belong to respiratory electron transport with the exception of DLD, which belongs to the TCA cycle." (PMID 34576238, 2021).
genetic disorder (2 papers, 2019 to 2022). "Dihydrolipoamide dehydrogenase (DLD) deficiency is a rare, autosomal recessive, genetic disorder caused by pathogenic variants in DLD." (PMID 36278487, 2022). "Dihydrolipoamide dehydrogenase (LADH, E3) deficiency is a rare (autosomal, recessive) genetic disorder generally presenting with an onset in the neonatal age and early death; the highest carrier rate has been found among Ashkenazi Jews." (PMID 30847858, 2019).
metabolic disease (2 papers, 2018 to 2023). A congenital disorder (due to inherited enzyme abnormality) or acquired (due to failure of a metabolically important organ) disorder resulting from an abnormal metabolic process. "Inherited mutations in the DLD gene are also associated with metabolic diseases that often present with severe neurological symptoms." (PMID 37920383, 2023).
neurodegenerative disease (1 paper, 2023). A disorder of the central nervous system characterized by gradual and progressive loss of neural tissue and neurologic function. "The GSEA results demonstrated that these 3 key genes (DLD, PLPP2, and PLAAT4) were all associated with neurodegenerative diseases, which supports the notion that the identification of these key genes was accurate to some extent." (PMID 37736681, 2023).
DLD also shares sentences with these, for which no sentence is quoted: thyroid cancer (3 papers); cholelithiasis (2); developmental delay (2); gastroenteritis (2); liver cancer (2); tuberculosis (2); age (1); Alexander disease (1); anisakiasis (1); benign prostatic hyperplasia (1); bone cancer (1); brain cancer (1); Cholecystitis (1); colitis (1); colon adenocarcinoma (1); colon cancer (1); diabetic cardiomyopathy (1); Dystonia (1); endometriosis (1); epilepsy (1); eye cancer (1); Friedreich ataxia (1); glycogen storage diseases (1); head and neck tumor (1); Hemoptysis (1); hepatitis C virus infection (1); Huntington disease (1); inflammatory bowel disease (1); kidney cancer (1); kidney diseases (1).
A further 28 diseases each share a sentence with DLD in 1 paper.